JUND (JunD proto-oncogene, AP-1 transcription factor subunit)
Diseases named in the same sentence as JUND in open-access papers (continued):
Sharing a sentence is not in itself a finding about the gene and the disease.
asthma (2 papers, 2022 to 2023). "Activation of Fhl2 by recall allergen stimuli downregulated Bach2 and JunD and activated the ERK1/2-AP1 and STAT6 pathways, inducing a memory-driven asthma phenotype." (PMID 36524132, 2022). "Similarly, expression of the prostaglandin receptor PTGER4 in the lung might be impacted by common deletions of JUND and SP1 binding sites (MAF = 14.2%), which might have important roles in the modulation of prostaglandins in allergic pulmonary inflammation and asthma." (PMID 37684227, 2023).
cervical cancer (2 papers, 2020 to 2021). A primary or metastatic malignant neoplasm involving the cervix. "Finally, using data from The Cancer Genome Atlas (TCGA), we observed that JUN expression significantly correlated with reduced survival in cervical cancer patients, whereas JUND expression did not." (PMID 33303976, 2021).
colorectal cancer (2 papers, 2021). A primary or metastatic malignant neoplasm that affects the colon or rectum. "Transcriptomic profiling confirms key regulatory targets of JunD, and a gene signature derived from the model demonstrates strong prognostic potential in TCGA colorectal cancer data." (PMID 33413550, 2021).
COVID-19 (2 papers, 2023). A disease caused by infection with severe acute respiratory syndrome coronavirus 2. "Patients with COVID-19 showed downregulation of genes involved in the AP-1 transcription factor pathway (including JUN, JUNB, JUND, and FOSB) as well as HLA genes (including HLA-E, HLA-DRB1, HLA-DRA, and HLA-DPB1)." (PMID 36992700, 2023). "Specifically, we found a set of 89 DE genes in COVID-19 macrophages from all three organs, including PLCG2, HIF1A, ACTB, and JUND." (PMID 37830426, 2023).
crescentic glomerulonephritis (2 papers, 2013). A histopathologic term for a pattern of diseases characterized by extensive crescent formation in the glomeruli; patients present clinically with rapid deterioration of renal function, and possible progression to end-stage renal failure within weeks or months. "We have previously shown that JunD is a determinant of the macrophage oxidative burst associated with crescentic glomerulonephritis." (PMID 23398888, 2013). "In crescentic glomerulonephritis JunD deficiency may cause increased oxidative stress in the glomerular podocytes, leading to altered VEGFA expression and subsequent glomerular injury." (PMID 23398888, 2013). "Our data also suggest a previously unappreciated contribution of the ATF complex to JunD-mediated mechanisms of macrophage activation in a rat model of crescentic glomerulonephritis." (PMID 24053712, 2013).
depression (2 papers, 2021 to 2026). "Within the AP-1 transcription factor family (including FOS, JUN, JUNB, and JUND), FOS expression is markedly reduced in stress-induced depressive mouse models, correlating with depression-like behaviors under chronic social defeat stress (CSDS)." (PMID 41479556, 2026).
endothelial dysfunction (2 papers, 2022 to 2023). In vascular diseases, endothelial dysfunction is a systemic pathological state of the endothelium (the inner lining of blood vessels) and can be broadly defined as an imbalance between vasodilating and vasoconstricting substances produced by (or acting on) the endothelium. "Activator protein-1 (AP-1) transcription factor JunD is deeply implicated in age-related disease due to its ability to regulate oxidative stress levels; its importance in the vascular context is supported by the observation that its overexpression can rescue endothelial dysfunction in aged mice." (PMID 36555671, 2022).
gastric cancer (2 papers, 2020 to 2024). A primary or metastatic malignant neoplasm involving the stomach. "GSVA analysis suggested that IL24 and JUND expression is significantly positively correlated with the metastasis process in gastric cancer." (PMID 39850884, 2024).
Hyperglycemia (2 papers, 2021 to 2024). An increased concentration of glucose in the blood. "Hyperglycemia promotes ROS production by downregulating JunD expression, which leads to cardiac dysfunction." (PMID 34335468, 2021).
lung adenocarcinoma (2 papers, 2012 to 2022). A carcinoma that arises from the lung and is characterized by the presence of malignant glandular epithelial cells. "Pulmonary cancer: curcumin improved the expression of cancer suppressor DnaJ-like heat shock protein 40 (HLJ1) via JNK/JunD pathway activation and prevent human lung adenocarcinoma cell invasion and metastasis via modulating E-cadherin expression." (PMID 36712505, 2022). "In summary, our results suggest that DMSO is an important stimulator of the tumor suppressor protein HLJ1 through JunB and JunD activation in the highly invasive lung adenocarcinoma CL1–5 cells." (PMID 22529897, 2012).
psoriasis (2 papers, 2021 to 2022). An autoimmune condition characterized by red, well-delineated plaques with silvery scales that are usually on the extensor surfaces and scalp. "JUND was also significantly up-regulated in all three syndromes of psoriasis, and current research shows that its encoded protein can inhibit cell apoptosis." (PMID 35126107, 2021). "Therefore, it is speculated that JUND may be involved in the pathogenesis of psoriasis and psoriatic arthritis." (PMID 35126107, 2021). "AP-1 transcription factor superfamily (including JUN, JUNB, JUND, FOS, FOSB, FRA1, and FRA2) is essential in the pathogenesis of psoriasis." (PMID 35075118, 2022).
type 2 diabetes (2 papers, 2017 to 2021). "These signaling pathways contained the significant gene regulatory network of transcript factors families for type 2 diabetes including SP1, NFIC, ZFP161, and FOS, JUND, JUNB." (PMID 28179884, 2017). "Together, these results demonstrate the repressive role of the menin/JunD/Pbk axis in regulating HFD‐induced compensatory beta cell proliferation and pharmacologically regulating this axis may serve as a novel strategy for type 2 diabetes therapy." (PMID 33821572, 2021).
carcinoid (1 paper, 2016). "HOXC6 expression in cultured human BON1 carcinoid cells enhanced cell proliferation and activated the oncogenic activator protein-1 signaling pathway through JunD." (PMID 27081081, 2016).
chordoma (1 paper, 2022). Chordomas are rare malignant tumors arising from embryonic remnants of the notochord in axial skeleton. "miR-1908-5p targets TGF-β1 and JunD in the MAPK pathway to promote the proliferation of chordoma tissue." (PMID 35463352, 2022). "In chordoma, miR-1908-5p targets TGF-β and JunD, thereby inhibiting the JNK and p38 MAPK signaling." (PMID 35463352, 2022).
Cirrhosis (1 paper, 2022). A chronic disorder of the liver in which liver tissue becomes scarred and is partially replaced by regenerative nodules and fibrotic tissue resulting in loss of liver function. "Several oncogenic transcription factors (TFs) inferred with DoRothEA35 including FOS, ETS2, RELB, SOX10, ERG, WT1 and JUND and TFs supporting stemness such as PBPJ and ARID3A were upregulated in cirrhosis patients and correlated with bacterial translocation." (PMID 35803930, 2022).
diffuse large B-cell lymphoma (1 paper, 2020). "Studies have shown that the expression of JUND is positively correlated with tumor cell proliferation in diffuse large B-cell lymphomas." (PMID 32318351, 2020).
endometriosis (1 paper, 2008). The growth of functional endometrial tissue in anatomic sites outside the uterine body. "Furthermore, the proto-oncogenes AXL, SHC1, and JUND are elevated in endometriosis." (PMID 19055724, 2008).
esophageal cancer (1 paper, 2009). A primary or metastatic malignant neoplasm involving the esophagus. "Present investigation provides evidence of a constitutively activated AP-1 in esophageal cancers and demonstrates involvement of JunB, JunD and cFos as major DNA binding partners whereas it clearly negates the role of canonical AP-1 partner, cJun." (PMID 19758438, 2009).
glomerulonephritis (1 paper, 2017). A renal disorder characterized by damage in the glomeruli. "This was confirmed by ChIP-seq and RNA-seq analyses, showing differential transcription factor binding at the Ifitm3 promoter by JunD (an established determinant of glomerulonephritis), and a consistent change in Ifitm3 expression." (PMID 28213474, 2017).
Graves disease (1 paper, 2025). Graves' disease is an autoimmune disorder that leads to overactivity of the thyroid gland (hyperthyroidism).It is caused by an abnormal immune system response that causes the thyroid gland to produce too much thyroid hormones. "XIST, PPP1R2C, CALHM6, AL672277.1, TSIX, SHROOM1, ADTRP, JUND, SGK1, CHKA, AO008569.1, MAP7D2, and AIF1 were down-expressed genes in TS compared with both the healthy female and the female patient with Graves’ disease." (PMID 39851522, 2025).
hyperinsulinemic hypoglycemia (1 paper, 2021). An inherited autosomal recessive syndrome characterized by the disorganized formation of new islets in the pancreas and congenital hyperinsulinism. "JunD−/− mice have a shortened lifespan and develop hyperinsulinemic hypoglycemia, but the underlying mechanism was not clear." (PMID 33821572, 2021).
keratoconus (1 paper, 2020). A degenerative, structural disorder of the eye, characterized by a cone-shaped protrusion of the cornea. "The gene encoding cyclic AMP dependent transcription factor ATF3, decreased in both groups, regulates cell proliferation and differentiation, and is a stress response gene that interacts with JUN and FOS; additionally, related genes, JUND and FOLSL1 are both downregulated in the keratoconus samples." (PMID 32555404, 2020).
multiple endocrine neoplasia type 1 (1 paper, 2023). An autosomal dominant tumor predisposition syndrome caused by pathogenic variants in the MEN1 gene, characterized by an increased risk of tumors of the parathyroid glands, pituitary gland, and foregut neuroendocrine tumors (most commonly pancreatic islet cells). "Menin plays a dominant role in the pathogenesis of multiple endocrine neoplasia type 1, embryonic development, and in normal regulation of cell growth and/or survival with its ability to regulate the activity of multiple transcription factors, such as Smad 3, JunD and NF-κB21–24." (PMID 37291166, 2023).
non-alcoholic fatty liver disease (1 paper, 2021). "Besides, JunD has been proved to affect hepatic TG metabolism and non-alcoholic fatty liver disease (NAFLD)." (PMID 34335468, 2021).
osteoarthritis (1 paper, 2023). A noninflammatory degenerative joint disease occurring chiefly in older persons, characterized by degeneration of the articular cartilage, hypertrophy of bone at the margins and changes in the synovial membrane. "In osteoarthritis, JUND transcriptional activation acts on the LncRNA LOXL1-AS1 to promote chondrocyte proliferation and inflammation, leading to osteoarthritis progression." (PMID 37503333, 2023).
osteopetrosis (1 paper, 2020). Osteopetrosis, also known as marble bone disease, is a descriptive term that refers to a group of rare, heritable disorders of the skeleton characterized by increased bone density on radiographs. "They describe the embryonic lethality of cJun, JunB and Fra-1 (showing they are indispensable) but KO of any AP-1 causes some detrimental effect such as osteopetrosis (cFos KO) or male sterility (JunD KO)." (PMID 32917236, 2020).
ovarian carcinoma (1 paper, 2020). A malignant neoplasm originating from the surface ovarian epithelium. "We will further study the interaction between JUND/JUNB and MUC5B in vivo and in vitro to uncover the mechanism of chemotherapy sensitivity in ovarian cancer." (PMID 32441484, 2020).
pituitary (1 paper, 2025). "It is possible that the elevated risk for aggressive pituitary NETs in SHRs is associated with low expression of JunD, a transcription factor involved in inflammation and oxidative stress pathways, which is known to be deficient in SHRs due to a promoter polymorphism." (PMID 41203869, 2025).
prostate tumours (1 paper, 2021). "We found low-grade prostate tumours were significantly enriched for the AP-1 family of TF binding sites (JUN, JUNB, JUND and FOS, FOSB and FRA1, and the closely related activating TFs: ATF and CREB), in contrast to high-grade prostate tumours that were enriched for FOXA1, HOXB13 and CDX2." (PMID 34911933, 2021).
rheumatoid arthritis (1 paper, 2022). A chronic, systemic autoimmune disorder characterized by inflammation in the synovial membranes and articular surfaces. "Among PSA T and NK cells, we also observed a downregulation of AP-1 transcription factors (JUN, JUNB, JUND, FOS) and regulators of activation (TNFAIP3, DUSP1) along with the upregulation of S100A11, a calcium-binding protein associated with rheumatoid arthritis." (PMID 35309349, 2022).
rosacea (1 paper, 2021). A chronic erythematous skin disorder that affects the face. "Our results were consistent with the hypothesis that AP1 TFs (FOS, FOSB, JUN and JUND) were downregulated in rosacea lesions." (PMID 34290700, 2021).
Sepsis (1 paper, 2016). Sepsis is defined as life-threatening organ dysfunction caused by a dysregulated host response to infection. "JNK is activated during sepsis and phosphorylates the N-terminal transcriptional activation domains (TADs) of Jun family members, such as c-Jun, JunB, and JunD." (PMID 27011790, 2016).
Stroke (1 paper, 2020). Sudden impairment of blood flow to a part of the brain due to occlusion or rupture of an artery to the brain. "This research also found a significant under-representation of JunD, NCX3 and FGFR4 annotated to GO biological processes, which may significantly impact stroke pathophysiology and subsequent clinical outcomes." (PMID 33447134, 2020).
T cell lymphoma (1 paper, 2022). "The common related pathological pathways for both JUNB and JUND are oxidative stress and T cell lymphoma." (PMID 35341155, 2022).
thyroid cancer (1 paper, 2019). "Previous study also reported that the expression of c-Jun, JunD, and Fra-1 protein significantly increased in human thyroid cancer tissue and played a critical role in the process of thyroid cancer cell proliferation." (PMID 30704487, 2019).
yang deficiency (1 paper, 2022). Yang deficiency is a concept from traditional Chinese medicine. "The symptomatic gene targets for Yang deficiency (KAT2B, NFKB2, CREBBP, GTF2H3) or Yin deficiency (JUNB, JUND, NGLY1, TNF, RAF1, PPP1R15A) were potentially discovered." (PMID 35341155, 2022).
ZIKV infection (1 paper, 2018).
tumor (86 papers, 2005 to 2026). "Several missense mutations in MEN1 disrupt the menin–JunD interaction, suggesting a correlation between menin tumor suppressor function and its interaction with JunD to block JNK kinase-mediated JunD phosphorylation, which is critical for JunD activation." (PMID 39594699, 2024). "TFs of AP-1, regulating TNFα, IL-6 and SELE are implicated as oncogenes or tumor suppressors in many cancers with drug development programs targeting cJun, JunB, JunD, cFos, FosB, Fra1 and Fra2." (PMID 36371231, 2022). "Several MEN1 missense mutations disrupting menin–JunD interaction were identified, suggesting that the tumor-suppressive function of menin in the MEN1 syndrome is connected with the regulation of JunD-target genes." (PMID 31947537, 2020). "Specifically, the c-Jun AP-1 family member has been implicated in tumor progression, while the JUNB and JUND played tumor suppressor role." (PMID 32079144, 2020). "Deletion of the JunD gene in the stroma promoted tumor growth and metastasis, associated with increased ROS production, with consequent accumulation of HIF1α and HIF1α-dependent induction of CXCL12, activating CXCR4, promoting CAF differentiation." (PMID 29137220, 2017). "It is tempting to speculate that JNK signaling has tumor-suppressive effects through c-Jun and tumor-promoting effects through JunD and that loss of one arm tips the balance toward the effects of the other arm." (PMID 34236045, 2021). "Data mining indicated that JunD, a transcription factor binding AP-1 sites and implicated in various tumor types, may be responsible for regulating ZO-1, which is indispensable for TJ assembly and function." (PMID 34316331, 2021). "The discovery of CCR4 as a downstream target of FRA-2 and JUND could in the future be exploited, being a tumour-associated antigen in adult T-cell leukaemia/lymphoma (ATLL) and CTCLs." (PMID 29597249, 2018). "JUND, a member of the AP-1 transcription factor family, modulates tumor angiogenesis, differentiation, and proliferation, and is downregulated in chemotherapy-sensitive ovarian cancer patients." (PMID 39859203, 2025). "IHC staining confirmed dramatic upregulated nuclear cFos and JUND levels in Pb-Cre;Ptenfl/flArid1afl/fl at 13-and 6.5-fold respectively, when compared to control Pb-Cre;Ptenfl/fl and Pb-Cre;Ptenfl/flArid1afl/+ tumours." (PMID 39885328, 2025). "This enrichment of H3K4me3 is indicative of the activation of JunD transcription, potentially representing a novel regulatory mechanism through which tumor cells exert a direct influence on osteoclast activity." (PMID 39816691, 2025). "JUNB and JUND are credited with both tumor-suppressing and oncogenic roles, since the outcome of their activation relies on the specific cancer type, disease stage, intracellular localization, and the expression of interacting cofactors." (PMID 41020863, 2025). "In this study, Jun was tumour-suppressive, and its expression was inversely related to the JunD isoform in primary human LADC biopsy samples." (PMID 39859271, 2025). "We further investigate cFos and JUND protein levels in the murine tumours with varying Arid1a status." (PMID 39885328, 2025). "The enhanced JunD subsequently activates the transcription of SLC7A5 which promotes the tumor cells proliferation and avoids immune attack." (PMID 38402198, 2024). "Studies are warranted given many reports of RHA and JUND dysregulation in neoplasms and the important role we have identified for TGS1 in recovery from mTOR inhibition." (PMID 37386121, 2023). "We observed that loss of JunD significantly repressed the proliferation ability of CD8+ T cells and disturbed the tumor-lysis capacity of CD8+ T cells following DP treatment." (PMID 36853831, 2023).